PRH1 (proline rich protein HaeIII subfamily 1)
Description:
PRP's act as highly potent inhibitors of crystal growth of calcium phosphates. They provide a protective and reparative environment for dental enamel which is important for the integrity of the teeth.
Synonyms: Pa; PIF-S; Db-s; PRP-1/PRP-2; Pr1/Pr2
Gene: Protein-coding gene on chromosome 12 (10,824,960 to 11,171,608, reverse strand). Ensembl gene ENSG00000231887.
Subcellular location: Secreted
Genetic constraint (gnomAD): Loss-of-function variants: 7 observed, 7.91 expected, observed/expected ratio (o/e) 0.89, 90% interval 0.5 to 1.62. That is too few expected variants to judge how well the gene tolerates losing a copy. Missense variants: 109 observed, 205.19 expected, observed/expected ratio (o/e) 0.53, 90% interval 0.45 to 0.62. Synonymous variants: 45 observed, 73.25 expected, observed/expected ratio (o/e) 0.61, 90% interval 0.48 to 0.79.
Homologues: Paralogues in human: PRH2 (87% identical), PRB2 (61% identical), PRB3 (61% identical), PRB4 (56% identical), PRB1 (55% identical), PRR4 (30% identical).
Diseases named in the same sentence as PRH1 in open-access papers:
PRH1 is named in the same sentence as 4 diseases in open-access papers, as found by Europe PMC text mining. Sharing a sentence is not in itself a finding about the gene and the disease. The quoted sentences say what the papers report.
dental caries (2 papers, 2019 to 2024). The decay of a tooth, in which it becomes softened, discolored, and/or porous. "PRH1 is a parotid-specific gene with importance in innate defenses in the mouth and genetic variations are associated with risk for dental caries." (PMID 31404082, 2019). "Several previous studies have identified an association between several genes and dental caries, including genes related to enamel formation such as AMBN, AMELX, and ENAM; taste receptor genes such as TAS2R38, TAS1R2; immune-related genes such as HLA; and saliva genes such as MUC5B, PRH1." (PMID 38414691, 2024).
pneumonia (1 paper, 2020). An acute, acute and chronic, or chronic inflammation focally or diffusely affecting the lung parenchyma, caused by an infection in one or both of the lungs (by bacteria, viruses, fungi, or mycoplasma.). "In a same experiment, unimmunised and PRH1 virus-infected mouse group showed an obvious decrease of body weight, suggesting the occurrence of severe pneumonia." (PMID 32802975, 2020).
infection (2 papers, 2023 to 2024). The state of being infected such as from the introduction of a foreign agent such as serum, vaccine, antigenic substance or organism. "We therefore examined those adolescents with markedly high S. mutans levels at baseline alone and at 17 years of age in association with caries and infection with high-cariogenicity mixed or B-1 types and human PRH1, PRH2 susceptible or resistant phenotypes." (PMID 38364699, 2024). "In particular, all immunized mice with CCFkH5- or CCAnH7-VLP survived for 10 d under PRH1 and HKH5 virus challenge infections, and the plaque titers of those mice were less than the detection limit." (PMID 36344085, 2023). "At first, in a challenge with high-virulence viruses, PRH1 and HKH5, all unvaccinated mice died within 10 d post-infection." (PMID 36344085, 2023). "In addition, in that study, caries progression with the PRH1, PRH2 phenotypes P4a, P6, and P1 varied by infection status (+, –) with S. mutans and lactobacilli." (PMID 38364699, 2024).
cancer (1 paper, 2022). A tumor composed of atypical neoplastic, often pleomorphic cells that invade other tissues. "Furthermore, we found that genes including LINC02270, PRH1, and KLHL3 were affected by germline TE insertions in 16, 16, and 15 OS patients, respectively, although their cancer-associated functions have never been reported before." (PMID 35013466, 2022).